APOE (apolipoprotein E)
Diseases named in the same sentence as APOE in open-access papers (continued):
Sharing a sentence is not in itself a finding about the gene and the disease.
hyperlipidemia (continued). "Oral administration of high-doses of YNKB resulted in significant lipid-lowering activity against hyperlipidemia in apoE-deficient mice, which might be associated with the composition alterations of the gut microbiota and changes in serum metabolite levels." (PMID 31269076, 2019). "Rs7412 in the APOE gene was associated with Fram_CHD (P = 3.0E-12), total cholesterol (P = 2.9E-37), lipidemia (P = 6.2E-33) and Ideal7 (the American Heart Association’s “Life’s Simple Seven” score, i.e., total number of ideal risk behaviors or metrics for each of the seven) (P = 3.3E-14)." (PMID 30704471, 2019). "Oral administration of high-dose YNKB also showed significant lipid-lowering activity against hyperlipidemia in apoE-deficient mice, which might be associated with composition alterations of the gut microbiota and changes in serum metabolite abundances." (PMID 31269076, 2019). "As hyperlipidaemia could impair and perturb the periodicity of clock genes in cardiovascular tissues in apoE-deficient mice and VSMCs, we hypothesized the high cholesterol content in PVSMCs might lead to the disturbance of clock gene expression." (PMID 28693506, 2017). "It is suggested that apolipoprotein E polymorphism may influence the development of hyperlipidemia in ALL patients receiving Pegaspargase therapy." (PMID 26693361, 2015). "Indeed, previous studies have shown that prolonged hyperlipidemia impairs Treg cell functions and disrupts the balance of Treg/Th17 cells in apoE-Fcγ-chain-deficient hyperlipidemic mice." (PMID 24991091, 2014). "It should be also emphasized that previous studies indicated that high concentration of apoE in apoB-containing lipoproteins might be associated with hyperlipidemia and an increased risk of cardiovascular diseases." (PMID 24234844, 2014). "In contrast, disruption of total body APOE function, i.e. in genetically modified APOE knockout mice, is associated with severe hyperlipidemia and spontaneous development of atherosclerotic lesions already on a regular chow low fat diet without added cholesterol." (PMID 24265824, 2013). "These combined findings suggest that the enhanced glucocorticoid action may represent an inherited protective anti-inflammatory response to the genetic hyperlipidemia-associated pro-inflammatory / pro-atherogenic status in APOE knockout mice." (PMID 24265824, 2013). "Therefore, the inhibited immune response in ApoE−/− mice at 20 wks of age can be attributed to long term hyperlipidemia, which overcomes the effects of ApoE deficiency, leading to decreased cytokine release and iNOS production." (PMID 23977160, 2013). "The presence of the ε2 or ε4 allele in the apolipoprotein E gene has been associated with severe hypertriglyceridaemia, hypertriglyceridaemic pancreatitis during pregnancy and higher postprandial levels of hyperlipidaemia." (PMID 19534808, 2009). "Additionally, genetic susceptibility factors such as apolipoprotein E are closely associated with both hyperlipidemia and ADRD risk, which may further account for their frequent co-occurrence." (PMID 41479608, 2025). "Notably, both conditions share common risk factors, including APOE ε4, hyperlipidemia, and obesity." (PMID 39080712, 2024). "However, IH alone was reported to cause hyperlipidemia in ApoE−/− mice." (PMID 33897472, 2021). "In summary, the results of the present meta-analysis revealed that the C allele of APOA5 1131 T > C, the A allele at APOA1-75 bp, the APOB XbaI T allele, and the ε2 and ε4 alleles of APOE may represent genetic risk factors for susceptibility for hyperlipidemia." (PMID 33836655, 2021).
hyperlipidemia (continued). "Therefore, APOE gene polymorphisms can be considered to be closely associated with hyperlipidemia." (PMID 33836655, 2021). "The proband’s younger brother (II3) had nephrotic syndrome, and laboratory examination showed proteinuria, hypoalbuminemia, hyperlipidemia and a high level of apoB; the same apoE gene mutation was also detected, so we cannot exclude that the patient may be diagnosed with LPG." (PMID 31092271, 2019). "It is clear that the alleles of ApoE are associated with lipid abnormalities; however, in our study, about 2/3 patients in both two groups were diagnosed with hyperlipidemia and most of them has been treated with statins lipid-lowering drugs, which may affect statistics results." (PMID 28326331, 2017). "The importance of apoE was first established in peripheral lipid transport, in the context of hyperlipidemia, with the discovery that cholesterol-rich particles attached to arginine-rich proteins (apoE) were present in elevated levels in the plasma." (PMID 41596530, 2026). "Here we generated muFHR1-/- (the murine homolog of FHR1) knockout mice and then crossed them with ApoE-/- knockout mice (a model of human hyperlipidemia)." (PMID 41583528, 2026). "Functionally, administration of ALOS significantly attenuated hyperlipidemia and reduced atherosclerotic plaque burden in high-fat diet-fed ApoE-/- mice." (PMID 42067693, 2026). "This study demonstrates that Apoeshl mice are useful not only as a model for investigating the function of ApoE in hyperlipidaemia but also as a model for investigating the function of ApoE in the CNS." (PMID 40026711, 2025). "The main findings of this study are as follows: First, the reduction of serum TC, TG, and LDL-C levels in mice indicated that the GLXB herb pair significantly attenuated the development of hyperlipidemia in ApoE-/- mice." (PMID 41466480, 2025). "Spontaneous hyperlipidaemia in SHL mice, a natural mutant, is caused by ApoE deficiency due to mutations in the Apoe gene." (PMID 40026711, 2025). "In this study, concerning HFD-induced hyperlipidemia and AS in apoE−/− mice, our findings indicate that the blood lipids were abnormal and aortic plaque and liver fat lesions were obvious." (PMID 41464973, 2025). "At the very beginning, it was reported that Ang II can only induce AAA in apoE-/- mice, presumably the presence of hyperlipidemia was required because infusion of Ang II into apoE+/+ mice failed to generate aneurysm." (PMID 40440080, 2025). "In this study, we demonstrate that the combination of STZ and HFD induces a CVD model in ApoE−/− mice, leading to hyperlipidemia, hyperglycemia, cognitive and memory impairment, and hippocampal damage." (PMID 40867851, 2025). "This indicate that STS protects the relaxation function of aorta in APOE-/- mice with hyperlipidemia." (PMID 38992615, 2024). "Tail vein injection of PCSK9-D377Y AAV8 and western diet feeding induced hyperlipidaemia in C57 mice mimiced the hyperlipidaemic features of ApoE-/-." (PMID 38913045, 2024). "A follow up study utilizing the single-cell RNA technique would elucidate the hyperlipidemia molecular pathway of dogs by comparing human and dog ApoE mRNA concentrations at the tissue level individually." (PMID 39598239, 2024). "Secondly, for the first time, we demonstrated a correlation between hyperlipidemia and higher IOP in TAO and identified ApoE as an independent risk factor for the IOP levels." (PMID 39669501, 2024). "To further clarify the role of hyperlipidemia in hypertrophy-induced fibrosis, we performed scRNA-seq analysis of Cd34-CreERT2; Rosa26-tdTomato&ApoE-/- and Cd34-CreERT2; Rosa26-tdTomato mice after surgery." (PMID 39198543, 2024).
hyperlipidemia (continued). "We first chose the most classical way of modeling hyperlipidemia by feeding a high-fat diet to ApoE−/− mice." (PMID 38395998, 2024). "The upregulation of DIO2 gene expression was observed in ApoE mice with hyperlipidemia and AS in Western diets, indicating that DIO2 plays a certain role in the development of AS54." (PMID 38503760, 2024). "The young male patient is manifested with nephrotic syndrome, accompanied by hyperlipidemia with a preferable increase in triglycerides and elevated ApoE level." (PMID 38448817, 2024). "Genetic mutation and polymorphism on ApoA-1, ApoE, and LPL is also closely related to hyperlipidemia according to previous research by Baroni, 2003." (PMID 39598239, 2024). "To evaluate the impact of hyperlipidemia on muscle atrophy and the potential effects of ENT on the muscles of mice with hyperlipidemia, we employed APOE−/− mice and measured blood lipid levels." (PMID 39717825, 2024). "To explore the critical role of NLRP3 inflammasome in hyperlipidemia-induced relaxant function loss, we inhibited NLRP3 in ApoE-/- mice through MCC950 treating." (PMID 38992615, 2024). "Overall, we present the synergistic effect of wire injury and hyperlipidemia on lipoproteins deposition in the development of AVS in ApoE–/– mice, this model bear close resemblance to human AVS pathology." (PMID 36818346, 2023). "The diverse consequences of hyperlipidemia, including altered endothelial barrier function, inflammatory changes, and atherogenesis, prompted studies of ApoE−/−/VE‐PTPiECKO mice that were found to have less plasma leakage and atherogenesis." (PMID 36740996, 2023). "To develop a mouse model with rapid severe aortic valve stenosis and lipid deposition, we combined mechanical injury and hyperlipidemia in ApoE–/– knockout mice." (PMID 36818346, 2023). "We combined WI and hyperlipidemia in ApoE–/– mice to explore the synergistic effect on the stenosis of the aortic valve." (PMID 36818346, 2023). "In this study, after 8 weeks of feeding with a common diet, serum TC, TG and LDL-C in the model group were significantly increased and HDL-C was significantly decreased, indicating that ApoE-/- mice had serious hyperlipidemia." (PMID 36748219, 2023). "Our findings demonstrated that Apoeshl mice are useful as a model for investigating ApoE function in hyperlipidemia and in the central nervous system." (PMID 37396111, 2023). "In conclusion, this study demonstrated a synergistic effect of WI and hyperlipidemia on the development of AVS in ApoE–/– mice." (PMID 36818346, 2023). "Longitudinal studies of the effect of aging in the ApoE−/− model are confounded by length of time mice have been exposed to atherogenic stimuli (hyperlipidemia and low/oscillatory shear stress), making a true evaluation of the impact of aging per se difficult." (PMID 37086367, 2023). "In a mouse model of hyperlipidemia and hyperglycemia (apolipoprotein E/GPx1 (ApoE(−/−)GPx1(−/−))-double knockout (dKO) mice), ebselen significantly reduces NOX2 and oxidative stress ameliorating fibrosis and inflammation in the kidney." (PMID 36829988, 2023). "Upon WTD feeding, APOE*3-Leiden mice developed hyperlipidemia as reflected by a 10.7-fold increase in plasma cholesterol levels and 97% increase in triglyceride levels." (PMID 37175538, 2023).
hyperlipidemia (continued). "Although several studies have utilized the well characterized apolipoprotein E knockout mice (ApoE−/−), the use of ApoE−/− mice limits the experimental design because the timing of hyperlipidemia cannot be varied." (PMID 38164438, 2023). "While rodents are normally resistant to atherosclerotic plaque development, genetically modified strains such as the ApoE−/− mouse demonstrate hyperlipidemia and develop atherosclerotic lesions when fed an AD." (PMID 37086367, 2023). "Compared to ApoE−/− mice, an improvement in hyperlipidemia was observed in Irisin-ApoE−/− mice, and the irisin levels were negatively correlated with high-density lipoprotein cholesterol." (PMID 37645520, 2023). "Integrin β1+ macrophages are highly detectable in carotid plaques of the patients with hyperlipidemia or in atherosclerotic lesions of ApoE−/− mice." (PMID 36470423, 2022). "Compared to apoE-/- mice, apoE-/- mice treated with DEHP for 4 weeks exhibited aggravated hyperlipidemia, systemic inflammation and an atherosclerotic phenotype." (PMID 35264146, 2022). "Homozygous ApoE knockout rabbits developed mild hyperlipidemia on a chow diet but exhibited greater hyperlipidemia and aortic atherosclerosis on a cholesterol diet (0.3% cholesterol and 3% soybean oil) for 10 weeks." (PMID 36361754, 2022). "In our previous study, apoptosis of the SGNs appeared to be the main problem in ARHL of apolipoprotein E knockout (ApoE KO) mice with atherosclerotic development and hyperlipidemia." (PMID 36408520, 2022). "We chose ApoE–/– mice as our model, which developed hyperlipidemia that induced the occurrence and pathological course of MGD." (PMID 35721080, 2022). "In connection with this hypothesis, we recently identified apolipoprotein E (apoE) as a soluble receptor for pyrP and observed accelerated lysine N-pyrrolation associated with the accumulation of antibodies (Abs) against pyrP and DNA in apoE-deficient (apoE−/−) hyperlipidemia mice." (PMID 35031322, 2022). "With ApoE knockout, WD-induced hyperlipidemia (ApoE WD) resulted in significantly lower total SCFAs and propionate and butyrate levels than did the chow diet." (PMID 35256637, 2022). "The blood lipid level of each group was determined since it has been reported that a high-fat diet can lead to hyperlipidemia in ApoE−/− mice compared with a normal-chow diet." (PMID 35215505, 2022). "The sterile ApoE−/− mice treated with HFD had more severe hyperlipidemia and more atherosclerotic plaques than normal ApoE−/− mice." (PMID 36618709, 2022). "To determine the in vivo relevance of these results, we evaluated sXBP1 and cl-ATF6 α levels in the brachiocephalic artery of ApoE−/− mice with persistent hyperglycaemia or hyperlipidaemia." (PMID 35889743, 2022). "It was also observed that a small amount of apoE can be produced by macrophages, which was considered to play a role in suppressing hyperlipidemia and arteriosclerosis." (PMID 35602473, 2022). "In conclusion, the results of the present study showed that exercise treatment had a protective effect on hyperlipidemia-induced neuronal injury in ApoE−/− mice." (PMID 34409103, 2021). "AceK significantly increased the blood lipid levels in ApoE−/− mice, which led to a severe hyperlipidemia." (PMID 34836239, 2021). "Homozygous apoE KO rabbits on a normal diet only showed mild hyperlipidemia and their plasma total cholesterol levels reached ~200 mg/dL, similar to human type III hyperlipoproteinemia patients, whose cholesterol levels are elevated to 300~350 mg/dL." (PMID 33603774, 2021). "Adenine diet also worsened the hyperlipidemia phenotypes in apoE KO mice with increased plasma triglyceride, total cholesterol, and VLDL/IDL/LDL cholesterol levels compared to Con and Con + IMC groups." (PMID 33436815, 2021).
hyperlipidemia (continued). "A meta-analysis was conducted to explore the relationship between APOA (A1-75bp, A1 + 83 bp, A5–1131T>C), APOB (MspI, XbaI, EcorI), and APOE with hyperlipidemia so that an evidence-base can be provided for the prevention and control of hyperlipidemia." (PMID 33836655, 2021). "Correlations in the APOE genotype (E2/E2, E2/E3, E2/E4, E3/E4, E4/E4) and hyperlipidemia were analyzed using the wild type E3/E3 genotype as a reference." (PMID 33836655, 2021). "Serum lipid profiling showed significant hyperlipidemia in ApoE-/- mice fed with a high-fat diet, with serum levels of TC, TG, LDL-C, and ox-LDL significantly increased compared to the control group, and there was no change in HDL-C." (PMID 34775883, 2021). "Our previous report indicates that hyperlipidemia significantly induces mRNA transcripts of IL-35 and IL-35R subunits in ApoE–/– aortas." (PMID 34622804, 2021). "Hyperlipidemia upregulates 9 top immunosuppressive classes of genes in ApoE–/– Tregs compared with WT Tregs." (PMID 34622804, 2021). "The homozygous apoE knockout rabbits showed mild hyperlipidemia when fed a normal diet but developed much more severe hyperlipidemia when challenged with a cholesterol-rich diet, compared to the wild-type control rabbits." (PMID 33584832, 2021). "Deletion of apoE in mice even on a normal chow diet exhibited hyperlipidemia along with spontaneous aortic atherosclerosis." (PMID 33603774, 2021). "Taken together, this study of ApoE−/− mice demonstrated that obstructive MGD and hyperlipidemia are closely associated." (PMID 33233466, 2020). "Of note, the kinetics of the response to HLI in C57 wild-type mice and ApoE−/− mice appeared different, suggesting that hyperlipidemia stimuli inhibit angiogenesis." (PMID 33154757, 2020). "However, given the debatable role of hyperlipidaemia in aneurysm etiology and possible aggravation of aneurysm formation under Nrf2 transcriptional deficiency, in our study, we decided to replace ApoE KO mice with mice of normal lipid metabolism but fed them a fat-enriched diet." (PMID 32617140, 2020). "There have been many investigations that have proven that antioxidant administration decreases augmented lipid peroxide in diabetic rats and hyperlipidemia and vascular damage in ApoE-knockout mice." (PMID 32509990, 2020). "In this study, we showed that periodontal disease induced disturbance of gut microbiota in apoE−/− mice with hyperlipidemia." (PMID 33072621, 2020). "Of note, atherosclerotic lesions were more pronounced in ApoE-knockout mice (ApoE−/−), a widely employed animal model for hyperlipidemia, upon further deletion of TRPV1 (ApoE−/− TRPV1−/−)." (PMID 32471282, 2020). "We found that the levels of both miR-181a-5p and miR-181a-3p are decreased in the aorta plaque and plasma of apoE−/− mice in response to hyperlipidemia and in the plasma of patients with coronary artery disease." (PMID 31064980, 2019). "We then evaluated the effect of Irisin on hyperlipidemia in ApoE-/- mice fed a chow or Western diet." (PMID 31191305, 2019). "We established the GL261 model in syngeneic C57BL/6 mice, either wild-type (WT) on chow diet or Apolipoprotein E knock-out mice (ApoE−/−) that develop severe hyperlipidemia after a few weeks on high fat diet (HFD)." (PMID 31174567, 2019).